ADCY3 (adenylate cyclase 3)
Diseases named in the same sentence as ADCY3 in open-access papers (continued):
Sharing a sentence is not in itself a finding about the gene and the disease.
Obesity (continued). "For instance, homozygous ADCY3 pathogenic variants lead to severe obesity in the Pakistani population, a Swedish study of 630 men found that variants in the ADCY3 gene confer risk to obesity, and some ADCY3 variants are associated with adult-onset obesity in the Chinese Han population." (PMID 39519366, 2024). "Considering that some Adcy3 −/− mice display primary leptin resistance, it is tempting to propose that cAMP deficiency may underlie obesity by blunting anorexigenic downstream responses." (PMID 37064917, 2023). "In addition to obesity, loss of function mutations in ADCY3 cause anosmia in both mice and humans; unfortunately we did not perform a smell test in our patient." (PMID 37329217, 2023). "Altered autophagy due to a deficiency of ciliary ADCY3 may contribute to the development of obesity." (PMID 37064917, 2023). "The findings of this study suggest that intronic mutation in the ADCY3 gene may be an important statistically linked risk factor for obesity in the Labrador Retriever breed." (PMID 37368776, 2023). "The ADCY3 gene is associated with obesity and lipid metabolism." (PMID 36101325, 2022). "Whole body KO or knockdown of Adcy3 in ventromedial hypothalamus causes obesity." (PMID 36188604, 2022). "ADCY3 mutations play a pivotal role in neuronal primary cilia (microtubule-based cellular organelles) in neuronal function, which causes a predisposition to obesity." (PMID 36141228, 2022). "Polymorphisms in ADCY3 are associated with obesity in humans." (PMID 36568981, 2022). "The results of the eQTL and SMR analyses suggested that the RNAm-SNPs rs6713978 and rs13410999 may affect ADCY3 gene expression in these tissues and then affect obesity risk." (PMID 35879730, 2022). "In contrast, mice overexpressing the human ADCY3 gene and mice harboring a point mutation, which causes elevated enzymatic activity of ADCY3, are resistant to high fat diet-induced obesity." (PMID 36188604, 2022). "Interestingly, very recent studies linking novel ADCY3 variants to obesity and diabetes have been published, and ADCY3 gene mutations with loss of function have been identified in monogenic severe obesity." (PMID 34389046, 2021). "Besides its role in AAA progression, loss of ADCY3 increases the risk of obesity and type 2 diabetes, and the single nucleotide polymorphisms of this gene are related to hypertension, which are the risk factors leading to the initiation of AAA." (PMID 34068179, 2021). "In addition, ADCY3 gene polymorphisms were shown to be associated with obesity in patients with T2D; however, in this study, the impact of the gene variants on ADCY3 plasma or cellular levels were not explored." (PMID 32847122, 2020). "Interestingly, early onset of monogenic obesity is associated with homozygous mutations within the human ADCY3 gene, highlighting the role of ADCY3 in energy homeostasis." (PMID 32847122, 2020). "Adenylate cyclase 3 (ADCY3) product is primarily implicated in obesity onset." (PMID 33333988, 2020). "Furthermore, recent work has uncovered loss-of-function variants in ADCY3 associated with an increase in obesity levels." (PMID 30704512, 2019). "In human beings, loss of function variants of ADCY3 can increase risk of obesity and T2D." (PMID 30687391, 2018). "There is also some evidence to suggest that Adcy3 may play specific physiological roles in major depression and sleep disruption, which are disorders strongly associated with the obesity phenotype." (PMID 29921800, 2018). "Moreover, several GWAS have identified ADCY3 as a gene associated with obesity in adult and children populations." (PMID 29921800, 2018). "In addition to these loci, based on a loss-of-function screening of the same population, we recently identified a variant in ADCY3 recessively associated with obesity and type 2 diabetes." (PMID 29926116, 2018). "ADCY3/POMC has been implicated in obesity among children and adults." (PMID 28595647, 2017).
Obesity (continued). "According to recent studies, adenylate cyclase 3 (AC3) is associated with obesity." (PMID 28481334, 2017). "Although the role of Adcy3 in humans has yet to be elucidated, our findings raise the possibility that Adcy3 activators may be useful agents for the prevention or treatment of obesity and associated metabolic complications." (PMID 27678003, 2016). "Thus, we next tested if diet-induced obesity (DIO) could render Adcy3-AdcKO mice more susceptible to metabolic complications." (PMID 38684889, 2024). "Similarly, adenylate cyclase 3 (ADCY3) mutations have been implicated in obesity." (PMID 32698306, 2020). "Furthermore, previous studies have identified homozygous mutations in ADCY3 in children with severe obesity, and an ADCY3 variant has been associated with increased risk of obesity and type 2 diabetes in homozygous individuals and to a lesser degree in heterozygous carriers." (PMID 32153512, 2020). "Similarly, recent studies have identified a variant in ADCY3, which is widely distributed, high in subcutaneous and visceral adipose tissue, and associated with a significantly increased risk of obesity, and loss of function mutations in ADCY3 in mice leads to a severe obesity phenotype." (PMID 32698306, 2020). "For example, PEA induced the hypomethylation of Adyc3 promoter and abolished the G protein alpha pathway which influences Adcy3 activity, a known therapeutic target for obesity." (PMID 40153413, 2025). "Variants in three genes—ADCY3, GCK, and POMC—co-occurred with autosomal dominant mutations in key genes associated with both diabetes and obesity." (PMID 40149731, 2025). "Heterozygous carriage of recessive mutations was observed in the ADCY3 (adenylate cyclase 3), CEP290 (centrosomal protein), and TUB (Tubby-like protein) genes, which are involved in obesity pathogenesis." (PMID 40149731, 2025). "Genome-wide association studies (GWAS) have facilitated the discovery of genes that contribute to monogenic obesity, one of which is adenylyl cyclase 3 (ADCY3), a member of cyclases significantly associated with obesity." (PMID 39519366, 2024). "ADCY3 encodes an adenylate cyclase protein, which catalyzes synthesis of the important second messenger cyclic AMP and has been previously implicated in obesity." (PMID 38545620, 2024). "Recently, a study found that ADCY3 colocalizes with the MC4R gene, the most common cause of monogenic obesity, at the neural primary cilia in the hypothalamic neurons." (PMID 39519366, 2024). "Previous GWASs have demonstrated the association of the studied polymorphic loci ADCY3 rs1167627272, CLOCK rs1801260, FTO rs1421085, GPR61 rs41279738, RP11-775H9.2 rs1296328, SLC22A3 rs9364554, and TFAP2B rs734597 with obesity-related phenotypes." (PMID 39766774, 2024). "During our genetic screening, we identified a viable hypomorphic Adcy3-mutant mouse (Adcy3L278H/L278H) with massive obesity." (PMID 39137039, 2024). "Our findings contribute to existing research that supports the role of ADCY3 in the genetic pathogenesis of early-onset obesity." (PMID 39519366, 2024). "Through ENU screening, the authors identified an Adcy3-mutant mouse (Adcy3L278H/L278H) that develops obesity." (PMID 39352389, 2024). "Obesity and adiposity are influenced by genes like ADCY3, NPY2R, and SEC16B, which play central roles in MetS pathophysiology." (PMID 39858569, 2024). "A global knockout of Adcy3 in mice induces obesity characterized by hyperphagia and decreased physical activity." (PMID 37064917, 2023). "For instance, an obesity-related SNP near ADCY3 (Adenylate cyclase 3) was correlated with the methylation level of a nearby CpG site that was mapped to an enhancer region of this gene." (PMID 35986394, 2022). "We also showed that long-term α-cedrene administration protects rodents from HFD-induced obesity, and these positive outcomes induced by α-cedrene are largely diminished in Adcy3+/− mice." (PMID 34452275, 2021).
Obesity (continued). "Selective ablation of Adcy3 by injection of AAV-Cre into the VMH of Adcy3-floxed mice significantly increased body fat and led to obesity, supporting the idea that Adcy3 in the VMH plays an important role in the regulation of energy balance." (PMID 34211092, 2021). "In 2007, neuronal cilia were found to be specifically enriched with ADCY3, and it has subsequently been shown that global Adcy3-KO mice exhibit adult onset obesity due to disruption of cAMP signaling in the hypothalamus." (PMID 34211092, 2021). "Taken together, our data is in accordance with these reports, indicating a role for ADCY3 in obesity and T2D." (PMID 32847122, 2020). "Loss-of-function mutations in the ADCY3 gene, encoding for AC3, or loss of ADCY3 expression cause monogenic severe obesity and increase the risk for type 2 diabetes." (PMID 32579112, 2020). "Previous studies have shown that Adcy3 heterozygous null mice present with obesity, insulin resistance and increased adiposity." (PMID 32153512, 2020). "In fact, Mc4r and Adcy3 knockout mice exhibit similar phenotypes, including obesity and hyperinsulinemia." (PMID 29921800, 2018). "In accordance with the studies in humans, the Adcy3 knockout mice (Adcy3−/−) developed obesity characterized by an increase in fat mass and larger adipocytes." (PMID 29921800, 2018). "Particularly, they determined the significant correlation between a SNP (rs713586) associated with body mass index and DNA methylation in an enhancer region upstream of the adenylate cyclase 3 (ADCY3), a gene previously linked to obesity." (PMID 24822056, 2014). "ADCY3 knockout mice exhibit age-dependent obesity, which was attributed to hyperphagia, low locomotor activity, and leptin insensitivity and demonstrated to be most likely because of hypothalamic cAMP reductions." (PMID 25044758, 2014). "Notably, the associations of ADCY3 rs17799872 with MOD, SIRD, and SIDD suggest a shared genetic basis for obesity and glycemic dysregulation." (PMID 41153348, 2025). "The greatest increases in methylation in Wnt11, Celsr2 and Adcy3 could indicate future routes of investigation to elucidate the potential of PEA in NASH treatment, especially given their associations with obesity and diabetes." (PMID 40153413, 2025). "Additionally, mice with cilia dysfunction, such as adenylate cyclase 3 (AC3) deletion, displayed leptin resistance and obesity, indicating cilia involvement in leptin signaling." (PMID 41251447, 2025). "The role of ADCY3 as a circadian-regulated metabolic effector involved in thermogenic adaptation is further illuminated by its place in human history, which speaks to the broader debate on the origins of obesity-related genetic variation." (PMID 40766578, 2025). "Therefore, ADCY3 is an essential component of central mechanisms governing energy balance and represents a potential therapeutic target for obesity and related metabolic disorders." (PMID 41082226, 2025). "Notably, variants in the CDKAL1, ADCY3, ADRA2A, and NPY2R genes showed strong associations with metabolic traits such as waist circumference, insulin resistance, and obesity." (PMID 39858569, 2024). "ADCY3 plays an important role in the regulation of obesity and glucose homeostasis." (PMID 39060963, 2024). "Based on the evidence above, it can be hypothesized that folic acid supplementation may affect the methylation of the ADCY3 gene, thereby affecting the function of this gene and leading to obesity." (PMID 39060963, 2024). "Taken together, these findings demonstrate that loss of Gpr75 did not attenuate the obesity phenotype of Lepob- or Adcy3-mutant mice." (PMID 39137039, 2024). "We identified 2 novel variants in the adenylate cyclase 3 gene (ADCY3): a homozygous frameshift variant, c.2520C>G p.Thr840X, in a 4-year-old girl born to a consanguineous Pakistani parents who presented with severe obesity and signs of insulin resistance." (PMID 37329217, 2023).
Obesity (continued). "Mice lacking ADCY3 exhibit obesity that is caused by a decrease in activity, hyperphagia, and leptin resistance." (PMID 36568981, 2022). "Genes encoding leptin (LEP), leptin receptor (LEPR), melanocortin 4 receptor (MC4R), proprotein convertase subtilisin/kexin type 1 (PCSK1), proopiomelanocortin (POMC), kinase suppressor of ras 2 (KSR2), adenylate cyclase 3 (ADCY3), and others contribute to the development and progression of obesity." (PMID 36141228, 2022). "Inherited obesity and polygenic obesity (stemming from multiple and synergistic polymorphisms) are thought to involve brain, signaling, and nervous system genes such as NTRK2, KCNQ1, MRAP2, and ADCY3 that regulate satiety and thermo-caloric energy balance." (PMID 36143948, 2022). "Thus, rare variants within this locus impact obesity by making this site susceptible to methylation, which consequently attenuates the expression of POMC, ADCY3 and DNAJC27." (PMID 34207686, 2021). "In addition, ADCY3-knockout mice were found to be more vulnerable to obesity induced by a high-fat diet; meanwhile, the gain-of-function ADCY3M279I mutant protects animals from diet-induced metabolic imbalance." (PMID 32847122, 2020). "This is in line with the values of T2D incidence almost reduced by half in N_ITA with respect to S_ITA and may further support recent attention drawn by our best candidate gene (i.e., ADCY3) as a promising target for the development of anti-obesity drugs." (PMID 32438927, 2020). "For instance, ADCY3, an obesity related gene, plays a role in energy homeostasis." (PMID 30271426, 2018). "The causal genes might be ADCY3 and DNAJC27, which have previously been identified to be related to obesity and pubertal growth, respectively." (PMID 30271426, 2018). "In conclusion, these findings suggest that cAMP signals generated by Adcy3 in peripheral tissues may play a pivotal role in modulating obesity and insulin sensitivity." (PMID 27678003, 2016). "In addition, hepatic Adcy3 was reported to play a protective role in insulin resistance and obesity in mice with HFD-induced obesity." (PMID 27678003, 2016). "Recent studies have demonstrated that adenylate cyclase 3 (AC3) has a protective role in obesity." (PMID 26807509, 2016). "Adcy3+/− mice are vulnerable to obesity and metabolic diseases: body and adipose tissue weights and plasma levels of free fatty acids, cholesterol, triglycerides, and glucose were higher in Adcy3+/− mice relative to the wild type (both male and female) under conditions of HFD feeding." (PMID 39683011, 2024). "One or more of these approaches may allow Adcy3-targeted therapies to slow the obesity epidemic." (PMID 25329148, 2014). "Furthermore, studies using cord blood DNA samples and ADCY3-knockout mouse models discovered that increased methylation of genomic DNA sequences can lead to decreased activity of the ADCY3 gene and that decreased expression of the ADCY3 gene at the mRNA and protein levels contributes to obesity." (PMID 39126035, 2024). "Injection of ciliary ADCY3 inhibitor GPR88 resulted in obesity under normal chow and attenuated weight gain under HFD." (PMID 36568981, 2022). "In addition, we identified rare heterozygous missense variants in ADCY3 (p.G1110R), MYT1L (p.R807Q), ISL1 (p.I347F), LRP2 (p.R2479I, and p.N3315S) and a hemizygous missense variant in GRPR (p.L87M) (each in one patient), possibly contributing to the obesity phenotype in these patients." (PMID 32153512, 2020). "Genes in the leptin–melanocortin pathway, such as leptin (LEP), leptin receptor (LEPR), melanocortin-4 receptor (MC4R), adenylyl cyclase 3 (ADCY3), and brain-derived neurotrophic factor (BDNF) genes, are established contributors to obesity and insulin resistance." (PMID 38674857, 2024).
Obesity (continued). "Based on our results from Adcy3∆AT mice, pharmacologically inactivating Adcy3-at expression or impeding the interaction of AC3-AT with AC3 could pave the way to reactivate BAT function and mitigate obesity and obesity-related metabolic decline." (PMID 38684889, 2024). "Loss of GPR75 selectively inhibited weight gain in HFD-fed mice but failed to suppress the development of obesity in leptin ob–mutant (Lepob-mutant) mice and adenylate cyclase 3–mutant (Adcy3-mutant) mice on a chow diet." (PMID 39137039, 2024). "Male mice lacking Adcy3-at display increased energy expenditure and are resistant to obesity and ensuing metabolic imbalances." (PMID 38684889, 2024). "However, in the present study, the loss of GPR75 (Gpr75–/–) failed to inhibit the development of obesity in these chow diet–fed Lepob- and Adcy3-mutant mice." (PMID 39137039, 2024). "Similarly, we later demonstrated that haploinsufficiency of Adcy3 leads to obesity in the absence of hyperphagia in mice fed either HFD or chow." (PMID 34452275, 2021). "According to our data, Adcy3 had the same results at 12 weeks (p = 0.015) but not at 4 and 8 weeks, which indicated that Adcy3 might play a key role in preventing obesity in GK rats despite the hyperphagia from 8 weeks on." (PMID 27677945, 2016).
type 2 diabetes (15 papers, 2014 to 2025). "Moreover, recent human genetics studies have shown that mutations in ADCY3 are associated with type 2 diabetes." (PMID 38353726, 2024). "Furthermore, a common variation in ADCY5, a gene in the same family as ADCY3, is known to be associated with fasting plasma glucose levels and risk of type 2 diabetes." (PMID 37368776, 2023).